FGFR4 (fibroblast growth factor receptor 4)
Diseases named in the same sentence as FGFR4 in open-access papers (continued):
Sharing a sentence is not in itself a finding about the gene and the disease.
cancer (continued). "As a promising target, FGFR4 attracts intensive pharmaceutical and academic attention to develop novel target therapy against cancers driven by FGFR4." (PMID 30634399, 2019). "Compared with the other three FGFR family members, the signaling pathways and mechanisms of FGFR4 involved in cancer development are less characterized." (PMID 30634399, 2019). "Although the gene alteration is relatively low, FGFR4 overexpression has been reported in many types of cancer." (PMID 30634399, 2019). "This comprehensive review not only covers the recent discoveries in understanding FGFR4 regulation and function in cancer, but also reveals the therapeutic implications and applications regarding emerging anti-FGFR4 agents." (PMID 30634399, 2019). "In conclusion, the identified oncogenic FGFR4 activity explains mechanistically how RTKs such as FGFR4 can confer aggressiveness to certain cancer cells via apoptosis resistance." (PMID 30903103, 2019). "Despite these results, the molecular mechanisms explaining how FGFR4 confers aggressive cancer cell behavior remain incompletely understood." (PMID 30903103, 2019). "In contrast, cancer-associated FGFR4-R slightly induced MST2 cleavage (FGFR4-G/R vary in stability and signal output; endogenous FGFR4 in MDA-MB-453 contains G388R and the activating Y367C alterations)." (PMID 30903103, 2019). "FGFR4 is a highly versatile protein that has more than 20 known ligands, and is highly expressed in various types of cancer." (PMID 28445975, 2017). "The proposed methodology was applied to the determination of FGFR4 in raw lysates from 8 different cancer cells expressing variable amounts of the target receptor." (PMID 28376106, 2017). "The reasons why the FGFR4 rs351855 G>A polymorphism has opposite effects on different types of cancer are unclear, suggesting that other genetic and environmental factors might be involved, or that this polymorphism modifies cancer susceptibility in a tissue-specific manner." (PMID 28445975, 2017). "The applicability of this approach has been demonstrated through the accurate determination of the endogenous content of FGFR4 in 8 different cancer cell lysates." (PMID 28376106, 2017). "Determination of endogenous FGFR4 concentration (in pg μg-1) in different cancer cell lysates (2.5 μg)." (PMID 28376106, 2017). "The expression of FGFR1, FGFR2, and FGFR4 were higher in cancer tissues than in normal tissues, whereas the expression of FGFR3 was higher in normal tissues." (PMID 27154171, 2016). "Further study is needed to clarify this mechanism of action of FGF19/FGFR4 signaling on cancer stem cells within the fatty liver microenvironment as a risk factor for HCC." (PMID 27447573, 2016). "G388R sustains the activation of FGFR4, and human cancers characterized by this SNP were reported to be highly aggressive and metastatic in nature." (PMID 23900974, 2013). "Although the molecular basis of this function is still a matter of intense research, FGFR4 seems to play a role in a broader range of human cancers." (PMID 23226373, 2012). "These hits also provide ready targets such as the FGFR2, FGFR4, known oncogenes like MET, and the activin and ephrin receptors, that are likely to be linked to the oncogenic activation of the cancer tissues in which they are expressed." (PMID 23251904, 2012). "bFGF is related to the growth and shift of endotheliocyte and proteolysis.; in particular, it makes cancer cells grow by activating FGFR-4 (FGFs including FGF receptor-4)." (PMID 19671184, 2009). "Recent studies have focused on the possible implication of FGFR4 in the carcinogenesis of different cancers." (PMID 14710228, 2004). "Aberrant activation of the FGF19/FGFR4 signaling pathway has been identified in many cancers." (PMID 41328353, 2026). "Acquired resistance to FGFR4 inhibitors occurs when cancer cells adapt to their presence." (PMID 41328353, 2026).
cancer (continued). "The inhibition of FGF19, achieved through methods such as siRNA-mediated silencing or neutralization by an anti-FGF19 antibody, specifically decreases AKT phosphorylation, suppresses cancer cell growth, and enhances doxorubicin sensitivity in FGFR4+/FGF19+ BC cells." (PMID 41328353, 2026). "Importantly, both PDGFRB and FGFR4 have been investigated as potential therapeutic targets for cancer treatments, providing possible alternative avenues for targeted treatment in patients with these alterations." (PMID 41509216, 2025). "Moreover, these two SBS subtypes differed in somatic mutations in several cancer driver genes, including higher mutation frequency of ERBB2, GATA3 and FGFR4, and lower frequency of DMD, INHBA, OGDHL, PLEKHG5 and RYR2 in subtype 3 than in subtype 1 (P < 0.05)." (PMID 40858906, 2025). "Furthermore, decreased amounts of FGFR4 and F-19 were observed suggesting that the treatment affects cancer progressive markers." (PMID 41034324, 2025). "To investigate wich factors could modulate FGFR4 signalling in GC, we employed RNA-seq analysis on GC patients biopsies, human patients derived organoids (PDOs) and cancer cell lines." (PMID 37945798, 2024). "In addition, LRI-201 treatment also reversed the increment of MUC2 mRNA expression induced by LIF suggesting a potential role of the axis LIF/LIFR/FGFR4 in the onset of cancer." (PMID 37945798, 2024). "Targeting LIF/LIFR might avoid side effects linked to pan-FGFRs inhibitor and might be a promising therapeutic strategy for the treatment of cancers with aberrant FGFR4 activation." (PMID 37945798, 2024). "In addition, silencing or inhibiting FGFR4 in patients with CRC has been observed to make cancer cells more sensitive to two types of treatments against CRC: 5-FU (5-fluorouracil) and oxaliplatin." (PMID 38540215, 2024). "It is also noteworthy that FGFR4 represents an attractive new therapeutic target in cancer treatment, and several small kinase inhibitors are in preclinical and clinical development for the treatment of various cancers, including mCRC." (PMID 38650006, 2024). "Like other FGFR family members, FGFR4 has oncogenic roles in cancer." (PMID 36097178, 2022). "FGFR4 overexpression increases Bcl‐x expression through the MAPK cascade, implying that FGFR4 inhibitors combined with chemotherapeutic drugs could be useful for treating FGFR4‐overexpressing cancers." (PMID 35194944, 2022). "Fgfr4 codifies the fibroblast growth factor receptor 4 whose up-regulation has been demonstrated to have a role in glucose metabolism in cancer cells suggesting that Fgfr4 could also play a role in ASCs-D glucose metabolism." (PMID 35655589, 2022). "Therefore, targeting FGFR4 has been known as a promising therapeutic strategy for the development of small-molecule inhibitors for the treatment of cancers with aberrant FGFR4 activation." (PMID 36697897, 2022). "Thus, they are very specific for FGFR4 and constitute promising drugs against cancers driven by alterations in FGFR4." (PMID 36097178, 2022). "Similarly, amplification of FGFR4 gene is the predominant type and accounts for 78% of all FGFR4 gene alterations in various cancers." (PMID 35296193, 2022). "Besides the potential use of biologic agents such as blocking antibodies, there are several recently developed small molecule FGFR4-specific inhibitors being considered for cancer indications in patients." (PMID 35513431, 2022). "The stimulation of the FGFR4 pathway endows cancers with the capacity to resist chemotherapy." (PMID 35194944, 2022). "Three FGFR4 single-nucleotide polymorphisms (SNPs), including rs1966265, rs351855, and rs7708357, were evaluated in 413 CRC cases and 413 gender- and age-matched cancer-free controls." (PMID 34071523, 2021).
cancer (continued). "In the case of continuous dependence on oncogenes, the concept of differential resistance is of great significance for cancer treatment and contributes to the clinical progress of a new generation of FGFR4 inhibitors, which considers resistance mechanisms while maintaining selectivity for FGFR4." (PMID 33981224, 2021). "Considering the limitations of the current study, however, large prospective researches with genotyping of the whole FGFR4 locus are warranted to reveal the clinicopathological and prognostic roles of the FGFR4 Gly388Arg SNP among various types of cancer, histology, and ethnicity." (PMID 34737965, 2021). "FGFR4 is frequently overexpressed in various types of cancer." (PMID 34737965, 2021). "We proposed that FGFR4 might be important biomarker in cancer immunotherapy and the prognosis of NSCLC based on our work." (PMID 33407583, 2021). "FGFR4 expression in cancer tissue samples and PDOs was assessed by immunohistochemistry." (PMID 34344433, 2021). "Besides, the use of FGFR4 inhibitors remains a practical approach in cancer patients with high FGFR4 expression." (PMID 33981224, 2021). "Herein, we reviewed the clinical trial results for FGFR4 inhibitors for different cancer types." (PMID 33981224, 2021). "In breast cancer, FGFR4 resist cancer cell apoptosis by phosphorylating MST1." (PMID 32111983, 2020). "Thereby, the FGF19/FGFR4 axis is a potential therapeutic target in cancers." (PMID 32111983, 2020). "Overexpression of FGFR4 predict metastasis and poor survival outcome in various cancers." (PMID 33017009, 2020). "The variant FGFR4 p.Gly388Arg has been shown to penetrate the STAT3 molecule into the cell membrane and impact cell surface molecules, thereby accelerating the progression of cancer and becoming an important risk factor for the progression of the disease." (PMID 33456465, 2020). "FGFR4 consistently activated by amplified FGF19 has been identified in several types of cancer." (PMID 30634399, 2019). "High activation of FGFR4 is strongly associated with the amplification of its specific ligand FGF19 in many types of solid tumors and hematologic malignancies, where it acts as an oncogene driving the cancer development and progression." (PMID 30634399, 2019). "FGFR4 exerts a combination of biological effects that contribute to different hallmarks of cancer." (PMID 31167419, 2019). "Combined with the current study, these SNPs of FGFR4 may influence a broad spectrum of malignant neoplasm, which needs further investigation." (PMID 31878098, 2019). "These novel FGFR4-targeting therapies provide a novel and promising approach which could potentially be developed into a therapeutic strategy to combat cancer." (PMID 30634399, 2019). "Notably, patients with FGFR4 SNP rs351855 with homozygous AA were less likely to develop stage III or IV cancers." (PMID 29221201, 2017). "We found that FGFR4 mediates cancer cell survival predominantly via activation of PI3K/AKT." (PMID 27192118, 2016). "Aberrant FGFR4 signaling has been documented abundantly in various human cancers." (PMID 27618313, 2016). "There is no plausible biological hypothesis, or preclinical, data suggesting that palifermin would work as an anticancer drug for FGFR4-amplified cancers." (PMID 26980737, 2016). "Interestingly, FGFR4 proteins were found to be tyrosine-phosphorylated in cells that express them, suggesting that FGFR4 proteins are constitutively active in these cancer cells." (PMID 27192118, 2016). "The data from FGF19 expression with FGFR4 and EpCAM expression from the 24 immunohistochemically stained HCC sections were used to determine the correlation between FGF19 and its receptor FGFR4 and between the cancer stem cell marker EpCAM, respectively, in the ST-NASH-CR- HCC sequence." (PMID 27447573, 2016).
cancer (continued). "The results from the analysis of serum and tissues encouraged us to further analyze the histological distributions of FGF19 and its receptor FGFR4 as well as EpCAM, a potential cancer stem cell marker, corresponding to the clinical histological stages, including ST, NASH, CR and HCC." (PMID 27447573, 2016). "Different from other cancer types, blocking of FGFR4 has side effects for HCC patients." (PMID 26498355, 2016). "The mutation of FGFR4 V550L has a VAF = 0.95, indicating that the mutation happened before the uniparental disomy event of chromosome 5, which is estimated to occur at 26% of molecular cancer lifetime." (PMID 25768946, 2015). "FGFR4 expression is highly variable in most types of cancer." (PMID 22615798, 2012). "While the role of FGFR4 in cancer remains to be fully elucidated, several findings suggest that this receptor may be an important player in HCC development and/or progression." (PMID 22615798, 2012). "However, overexpression of FGFR4 has been shown in various cancers, including pituitary, prostate, thyroid." (PMID 17207284, 2007). "However, it has been shown that cancer cells ectopically expressing FGFR4 Arg388 possessed increased cell motility as well as invasiveness." (PMID 16721364, 2006). "However, further studies are needed to explore the role of this mutation as a molecular marker and the possible value of the FGFR4 gene or protein as a target for cancer therapy." (PMID 14710228, 2004). "In addition, FGFR4 inhibition has been studied in cancer, though whether FGFR4 is a suitable target in cancer therapy is still controversial." (PMID 38916962, 2024). "Although the FGFR4 mediated-benign hepatic TG storage might provide protection on hepatocytes, continuously up-regulated FGFR4 signaling could play a deleterious role contributing to cell proliferation and progression of cancers." (PMID 34326695, 2021). "Further investigations are needed to explore more details about the melatonin-FGF19/FGFR4 network, which may help us to obtain a better understanding on cancer progression and find more approaches to tackle malignant tumors, not only in the head and neck but also in other systems." (PMID 34576070, 2021). "Thus, FGFR4 would protect against cancer due to the interaction of FGFR4 with the β-klotho." (PMID 34200439, 2021). "Similarly, a single-nucleotide polymorphism (SNP) in FGFR4 (rs351855, causing G388R substitution) is associated with many types of cancers and increases the recruitment and activation of STAT3, thereby enhancing cancer progression." (PMID 33535617, 2021). "The FGF19/FGFR4 pathway could be an alternative target for cancer prevention and management." (PMID 34576070, 2021). "Additionally, Fgfr4 was −15.2-fold and −18.6-fold down-regulated in cancer." (PMID 19812696, 2009). "Subsequently, we explore its roles in various cancers and discuss the therapeutic applications of targeting the FGF19/FGFR4 signaling pathway in cancer treatment." (PMID 41328353, 2026). "In the field of cancer research and treatment, CRISPR-Cas9 provides new avenues for targeted therapies, exemplified by studies on the FGF19/FGFR4 signaling axis." (PMID 41328353, 2026). "However, it remains unknown which of the many point mutations affecting FGFR1, FGFR2, FGFR3 or FGFR4 in cancer are druggable, that is, activating signaling while not mediating FGFR inhibitor resistance." (PMID 41361008, 2026). "FGFR4 activation influences key oncogenic pathways such as the MAPK/ERK and PI3K/AKT signaling, which enhance cancer cell proliferation and survival." (PMID 40806692, 2025). "This disrupts its downstream pathways (FGFR4-JAK1-STAT3, FGFR4-AKT, and FGFR4-ERK), which helps inhibit cancer cell proliferation and resistance to apoptosis." (PMID 40091020, 2025). "FGFR inhibitors have been approved for the treatment of various cancers and a STAT3-dependent regulation of FGFR4 has been documented in the H.pylori infected intestinal GC." (PMID 37945798, 2024).
cancer (continued). "Present findings ground the basis for exploiting LIFR antagonists in the treatment of FGFR4-related conditions overcoming limits and side effects of pan-FGFR inhibitors in cancer treatment." (PMID 37945798, 2024). "In the present study, we report that the transcriptome analysis of cancer tissues from a cohort of locally advanced GCs express a dysregulated expression of LIF/LIFR and FGFR4." (PMID 37945798, 2024). "After cancer progression, the patient participated in a clinical trial of ABSK-011, a novel fibroblast growth factor receptor 4 inhibitor, with a frustrating result." (PMID 38728500, 2024). "SOX18 is a profound oncogene in many cancers, and FGF19/FGFR4 was found to upregulate SOX18 potentially through an interplay with Wnt signaling, specifically through the p-FRS2/p-GSK3β/β-catenin axis." (PMID 39796710, 2024). "In one study, FGFR4 overexpression was identified as a prognostic marker in advanced stage HGSC, and silencing of the receptor was shown to decrease cancer cell growth in vitro and in a mouse model." (PMID 37789421, 2023). "Previous studies have shown that FGFR4 and EZH2 inhibitors can induce cell apoptosis in various cancer cells." (PMID 37085881, 2023). "According to the Cancer Therapeutics Response Portal (CTRP) database, cells with resistance to lapatinib (an anti-HER2 inhibitor) had higher levels of FGFR4 expression." (PMID 35562334, 2022). "The SNP Gly388Arg at the transmembrane domain of FGFR4, a hot spot in RTKs, can enhance STAT3 activity by exposing a membrane proximal STAT3 binding site and finally accelerates cancer progression." (PMID 35701820, 2022). "All of FGF19, FGFR4, and KLB expression levels are greater in cancer tissues than in normal tissues next to malignancy." (PMID 36532586, 2022). "Although FGFR4 is identified as the last discovered FGFR, its dysregulation in cancers has been reported in many studies in recent years." (PMID 34400727, 2021). "In stratification analysis by ethnicity, we observed that FGFR4 V10I mutation may not have an impact on the risk of cancer for Asian (95%CI = 0.66–1.08, P = 0.184), African (95%CI = 0.34–1.86, P = 0.598), or individuals with European descent (95%CI = 0.83–1.42, P = 0.563)." (PMID 33446698, 2021). "The involvement in FGF15/19 and/or FGFR4 in cancer has been extensively reported, but the pathways and mechanisms by which FGF15/19 and/or FGFR4 affect tumorigenesis remains elusive." (PMID 34200439, 2021). "In addition, studies based on mouse models indicate that individual overexpression of FGF19 and/or FGFR4 are not the only risk factors for HCC and other cancer types since FGFR4 hyperactivation mediated by abnormal FGF19 expression and, consequently, signaling is just an important issue." (PMID 34200439, 2021). "FGFR4 upon ligation with FGF19 is known to promote drug resistance, cancer progression and metastasis." (PMID 34540690, 2021). "Thus, targeting FGF19/FGFR4 could be a promising approach to combat cancers." (PMID 34576070, 2021). "Several selective small molecule inhibitors of FGFR4 have been developed whose efficacy in HCC and various other cancers is currently being evaluated in early phase clinical trials." (PMID 34540690, 2021). "Although measures of FGFR4 levels in CRC through IHC remains limited, its elevation in other cancers and early evaluation of its protein levels at the cell surface suggests that FGFR4 should continue to be assessed as a CRC biomarker." (PMID 34290978, 2021). "In contrast, elevated expression of KLB and FGFR4 was reported in HCC, suggesting dual functions of KLB in cancer development and progression." (PMID 32154250, 2020). "Downstream pathways of FGF19/FGFR4 signaling, such as PI3K-AKT and MEK-ERK, lead to enhanced cell proliferation and survival in cancer cells." (PMID 33066597, 2020).